INS (insulin)
Diseases named in the same sentence as INS in open-access papers (continued):
Sharing a sentence is not in itself a finding about the gene and the disease.
Obesity (continued). "Several obesity-related host factors can influence breast tumor initiation, progression, and/or response to therapy including insulin, insulin-like growth factor-1, leptin, adiponectin, steroid hormones, cytokines, vascular regulators, and inflammation-related molecules." (PMID 25110685, 2014). "Thus these results indicate that while whole bilberries are effective in increasing insulin sensitivity at the early stages of obesity, they are unable to counteract the disturbance produced over a longer period of HFD feeding." (PMID 25501421, 2014). "Leptin biosynthesis is in close direct correlation with insulin level and this may explain the increased leptin levels observed in obesity." (PMID 23061769, 2013). "The secretion profile of pro and anti-inflammatory cytokines is altered in obesity and may directly impact insulin sensitivity." (PMID 24205333, 2013). "In obesity, excessive oxidative stress, intense inflammatory activity, insulin resistance, deregulated lipid metabolism, altered glucose metabolism, and impaired mitochondrial biogenesis are among the pathophysiological driving forces that precede the early stages of cardiac dysfunction." (PMID 24454978, 2013). "That finding might suggest that the influence of obesity on cancer mortality is mediated by excess insulin secretion." (PMID 23405181, 2013). "In a case-cohort study insulin and IGF-I levels were positively associated with breast cancer risk suggesting that hyperinsulinemia may be a substantial link between obesity and mammary carcinogenesis." (PMID 23061769, 2013). "We conclude that perturbations in insulin signaling and cardiac function may be forerunners to overt hyperglycemia and heart failure in obesity." (PMID 24454978, 2013). "Protein tyrosine phosphatase 1B (PTP1B), an intracellular nonreceptor PTPase, has received much attention due to its pivotal role in type II diabetes and obesity as a negative regulator of the insulin signaling pathway by dephosphorylating the activated insulin receptor." (PMID 24366088, 2013). "Metabolic disturbances/dysregulation of markers such as insulin, leptin, glucose, or tryptophan/serotonin could explain the link between obesity, DM2, and depression." (PMID 24229349, 2013). "During the progression of obesity, both the adipocyte and the stroma vascular fractions are changed: adipocytes grow larger, secrete predominantly proinflammatory cytokines, and are insulin resistant; coincidently, the nature of WAT immune cells is also modified." (PMID 24455420, 2013). "However, as shown here, vitamin D deficiency had the most pronounced effect either on insulin secretion by the pancreatic cells in people with normal weight, or, in the case of overweight or obesity, it lead to low tissue insulin sensitivity." (PMID 23924693, 2013). "CCDC80 is a secreted protein that regulates adipocyte differentiation, whereas DGAT2 is an enzyme that catalyzes the final step of mammalian triglyceride synthesis and may be involved in the mechanisms of obesity, insulin resistance, and leptin resistance." (PMID 23741331, 2013). "In contrast, studies in other Japanese, Caucasians, and African-American cohorts have not found an association of T2DM, insulin levels, or obesity with the Thr54 variant." (PMID 24156506, 2013). "Obesity is accompanied by infiltration of proinflammatory macrophages into adipose tissue; these cells secrete inflammatory cytokines, such as TNFα, which generate insulin resistance by stimulating catabolic pathways." (PMID 24368730, 2013). "Obesity may reduce insulin sensitivity, enhance free fatty acid turnover, increase basal sympathetic tone, induce a hypercoagulable state, and promote systemic inflammation." (PMID 24198964, 2013). "Specifically, muscle-specific JNK-1-deficiency left body weight gain and glucose tolerance unaltered during the course of obesity, but ameliorated insulin sensitivity and insulin-stimulated AKT phosphorylation in liver and WAT but not in the JNK-1-deficient muscle." (PMID 23349837, 2013).
Obesity (continued). "However, an excessive ponderal index, a more precise measure of obesity in pediatrics, was found in three newborns of women with a worse metabolic control and higher insulin requirement, all belonging to the NPHg." (PMID 23840206, 2013). "Moreover T regs were specifically reduced in the abdominal site in insulin-resistant models of obesity, with a mechanism related, at least in part, to the suppressive ability of leptin on T reg proliferation." (PMID 24084730, 2013). "In the present study, we showed that rosiglitazone, a PPARγ agonist, could reduce obesity-induced systemic inflammation, insulin resistance, macrophage accumulation and atherosclerotic plaque formation." (PMID 23620818, 2013). "Therefore, the purpose of this study was to examine the impact of obesity on circulating S1P concentration and its relationship with markers of glucose metabolism and insulin sensitivity." (PMID 24039766, 2013). "Diet-induced obesity in mice and humans is associated with increased ERK1 activity in adipose tissue, whereas Erk1−/− mice appear resistant to diet-induced obesity and remain insulin sensitive on a high-fat diet." (PMID 24209692, 2013). "Dysfunctional lipid metabolism accompanies obesity and can impair insulin signaling; circulating free fatty acids (FFAs) have a negative effect on insulin target tissues, through the activation of inflammatory pathways, via cell surface pattern recognition receptors (PRRs)." (PMID 23675368, 2013). "Fasting insulin levels differed significantly in the obesity compared with other groups." (PMID 23383064, 2013). "In obesity, an increase in iNOS expression is also observed in insulin sensitive tissues, which promotes a phenomenon known as S-nitrosation/S-nitrosylation, where nitric oxide (NO) reacts with cysteine residues to form S-nitrosothiol adducts, thereby modulating protein function." (PMID 23840101, 2013). "Genetic disruption of AMPK specifically in POMC or AgRP neurons causes obesity or resistance to obesity, respectively, while the neurons themselves maintain the ability to respond to insulin and leptin but not glucose." (PMID 23550218, 2013). "Plasma leptin and insulin were both elevated in our experimental model of diet-induced obesity." (PMID 23555678, 2013). "Moreover, calcidiol levels in women with normal weight was inversely proportional to HOMA-B values (r=-0.48, p<0.01), and for those with overweight and obesity they were directly proportional to insulin sensitivity index (r=0.28, p<0.01)." (PMID 23924693, 2013). "In addition, mast cells, eosinophils, and dendritic cells are also critically involved in obesity-induced inflammation and insulin resistance through the production of pro- and anti-inflammatory cytokines in adipose tissues." (PMID 23781214, 2013). "T2D is usually a non-insulin-dependent diabetes, generally associated with obesity, caused by deficient insulin secretion by pancreatic beta-cell islets or deficient insulin action in peripheral tissues." (PMID 24279768, 2013). "Interestingly, high metabolic process and obesity, which are induced due to high nutritional intake, also result in ER stress which suppresses insulin signaling." (PMID 24101950, 2013). "The influence of excess iron in a diet high in fat, fructose, and salt on metabolic changes—including decreases in obesity index, insulin, and nitric oxide serum concentrations, as well as increases in the relative mass of gonads—is a novel finding of this study." (PMID 23179349, 2013). "Furthermore, we examined pharmacokinetics and pharmacodynamics and monitored growth of MC38 cell allografts in mice with diet-induced obesity treated with human insulin, X10 and IGF-1." (PMID 24260289, 2013). "Thus, novel strategies capable of potentiating the HO-adiponectin-ANP axis would improve cardiomyopathy and insulin signaling in obesity." (PMID 24454978, 2013). "NEFAs are increased in obesity and are inversely correlated with insulin sensitivity." (PMID 24288531, 2013).
Obesity (continued). "In contrast with the improved insulin sensitivity seen after chronic GLP-1 or exendin-4 treatment in human patients with extreme obesity or T2DM, insulin sensitivity was profoundly decreased on the 11th day of exendin-4 treatment in neonatal IUGR lambs, relative to their untreated IUGR littermates." (PMID 23424667, 2013). "Further studies conducted in a mouse model of non-alcoholic steatohepatitis, indicated that linagliptin improves insulin sensitivity and hepatic steatosis in mice with diet-induced obesity and may ameliorate liver inflammation." (PMID 24264040, 2013). "Obesity increases cardiovascular risk through risk factors such as increased fasting plasma triglycerides, high LDL cholesterol, low HDL cholesterol, elevated blood glucose and insulin levels and high blood pressure." (PMID 23584084, 2013). "Moreover, in humans approximately 20% of the obese population remains fully insulin sensitive and metabolically normal, termed metabolically benign obesity." (PMID 23781214, 2013). "Obesity is characterized by chronic subclinical inflammation that affects insulin activity in its metabolically sensitive tissues, notably the liver, muscle, and adipose tissue, and drives a metabolic disorder that culminates in the deregulation of glucose homeostasis." (PMID 23840101, 2013). "Importantly, exogenous administration of leptin to Lepob/Lepob mice reduces obesity and restores insulin sensitivity." (PMID 23781214, 2013). "The authors used Recon 1 and GIMME to produce 42 context-specific models of human myocytes using three gene expression datasets (gastric bypass, glucose/insulin infusion, and obesity) and the metabolic requirement of at least sub-optimal ATP producing capabilities." (PMID 23630502, 2013). "Circulating ucOC is predicted by androgen excess in lean women and may stimulate compensatory insulin secretion within the bone-pancreas loop, a mechanism altered by presence of obesity." (PMID 23339653, 2013). "Leucine supplementation might have therapeutic potential in preventing diet-induced obesity and improving insulin sensitivity." (PMID 24086364, 2013). "The development of CVD may be mediated through obesity, decreased insulin sensitivity, dyslipidemia, or high blood pressure." (PMID 23483954, 2013). "In addition to pro-inflammatory cytokines, elevated levels of insulin, which can stimulate pro-survival and growth signaling in epithelial cells, is a key candidate for mediating the effect of obesity on colon cancer development." (PMID 23560112, 2013). "Conversely, obesity may downregulate the secretion of adiponectin, an adipokine with anti-inflammatory, insulin sensitizing and anti-tumor properties." (PMID 23061769, 2013). "In conclusion, our results suggested that the presence of the Ala allele may contribute to improved insulin secretory capacity and may confer protection from T2DM and obesity in the Chinese population." (PMID 23991018, 2013). "Obesity also increases insulin demand therefore hyperfunction of beta cells may exhaust beta cells resulting in beta cell dysfunction." (PMID 23542897, 2013). "As the amount of adipose tissue is very important in severe obesity, Munc18c from adipose tissue could play a relevant role in the regulation of insulin-stimulated exocytosis of GLUT4-containing vesicles." (PMID 23700440, 2013). "The data provided a system in which R/cape analysis could exploit both the identical and distinct factors contributing to obesity, glucose levels, and insulin regulation in deriving a polygenic model." (PMID 24204223, 2013). "A few studies have investigated metabolic signatures in relation to insulin sensitivity or obesity." (PMID 24330454, 2013). "There is an increase in food intake in Pomc−/−Tg+ compared with global Pomc nulls, the metabolic rate is decreased as indicated by reduced oxygen consumption (VO2) and an increased respiratory exchange ratio (referred to as RQ in this instance), and basal insulin levels are increased in obesity." (PMID 23649822, 2013).
Obesity (continued). "Exposure to endocrine disruptors such as stress and food contaminants, which have an effect on the regular activity of estrogens, androgens, and insulin may also affect the simultaneous development of obesity and cancer." (PMID 24073332, 2013). "In addition to insulin, leptin can also be a link between obesity and increased sympathetic activity." (PMID 23573411, 2013). "Additionally, blockages of HGF receptor (Met) worsen the already impaired insulin-induced insulin signaling in the liver of diet-induced obesity rats." (PMID 24133484, 2013). "This suggests that obesity-induced IL-6 secretion may reflect a mechanism to increase insulin production in the obese IR state." (PMID 23675368, 2013). "It is not easy to reconcile these findings, but it can be speculated that a threshold of obesity may exist, above which muscle ceramide accumulates and influences insulin signaling and thus insulin sensitivity." (PMID 23776659, 2013). "Exactly how a retinal protein affects obesity is unclear, but models of Bardet-Biedl syndrome suggest that ciliated sensory cells oversecrete peptides (e.g., insulin), which may explain the dual nature of the phenotype." (PMID 23922663, 2013). "NITKO mice of both sexes developed diet-sensitive obesity, increased plasma leptin levels, and increased plasma insulin level, indicating an important role for insulin receptor in the regulation of energy disposal, energy metabolism and perhaps also in reproduction." (PMID 23557393, 2013). "Interestingly, cancer cells commonly have the ability to respond to the activation effect of insulin on intracellular transduction pathways, particularly when insulin is highly concentrated, as occurs in obesity." (PMID 24073332, 2013). "Following the onset of obesity, mutant mice develop insulin resistance, increased glucose tolerance, and changes in blood biochemistry such as increased leptin, adrenocorticotropic hormone and insulin levels." (PMID 23649822, 2013). "Therefore this study will unveil the multifaceted mechanisms by which hemin therapy improves cardiac function and insulin signaling in obesity." (PMID 24454978, 2013). "Furthermore, animal treatment with chemical chaperones that alleviated obesity-induced ER stress led to improvement in insulin sensitivity." (PMID 24101950, 2013). "Regarding obesity, miRNAs seem to participate in the regulation of several important biological processes, such as adipocyte differentiation, metabolic integration, fat metabolism and insulin sensitivity." (PMID 23335998, 2013). "Many cell types have been proposed to influence insulin resistance in obesity." (PMID 23562076, 2013). "The major conclusion of this study is that within AA but not EA women, obesity predisposition appears related to insulin sensitivity, and that this predisposition is exacerbated by a high insulin response." (PMID 23298367, 2013). "Although the acute effect of pharmacological doses of epinephrine is to increase blood glucose and diminish insulin sensitivity, the long-term effect of endogenous epinephrine is reportedly protection against hyperglycemia and insulin insensitivity in a hig-fat-diet-induced obesity mouse model." (PMID 23837045, 2013). "Whether healthy obese individuals can maintain insulin sensitivity during the entire life or whether healthy obesity simply represents delayed onset of obesity related cardiometabolic complications has to be clarified." (PMID 24454978, 2013). "Thus, ROS overproduction results in I.R. In mice, ROS overproduction in target organs of insulin, like adipose tissue and liver, preceded the onset of obesity and I.R.." (PMID 24288531, 2013). "Göttingen minipigs have been used as obesity models and displayed minor abnormalities in glucose tolerance and insulin sensitivity, however the metabolic changes in lean and obese Göttingen minipigs on the diets used in the present study are not well described." (PMID 23437186, 2013).
Obesity (continued). "This might be due to an increase in weight while height is constant results in overweight or obesity, which could lead to insulin resistances and ultimately poor glycemic control." (PMID 23620789, 2013). "Thus, hyperphagia and obesity observed in IRS2-KO mice was paralleled with the impaired sensing of insulin by NG neuron." (PMID 23840624, 2013). "Finally, in adult flies, high fat diets (HFDs) and high sugar diets (HSDs) induce obesity and insulin resistance, suggesting that the molecular mechanisms of insulin resistance are conserved." (PMID 23587196, 2013). "Previous data from our laboratory displayed that impaired myocardial insulin signaling may play a critical role in contractile dysfunction in obesity." (PMID 23667647, 2013). "Thus, we recommend a more careful and restricted use of milk proteins, especially in the setting of pre-existent obesity, insulin resistance as well as sedentary life style." (PMID 24225036, 2013). "We cannot exclude the possibility that the recruited macrophages in the muscles are localised to the intermuscular adipose depots (which are known to accumulate in obesity) and could therefore contribute to insulin resistance through a paracrine mechanism." (PMID 23393605, 2013). "Considering that adiponectin has been recognized as a significant insulin sensitizer it would be consistent to anticipate that circulating adiponectin levels would be considerable in the presence of an insulin resistant state such as obesity." (PMID 24023698, 2013). "Mice deficient of S6K are protected against diet-induced obesity and show enhanced insulin sensitivity owing to the loss of the negative feedback loop from S6K to IRS1." (PMID 24391749, 2013). "A growing literature is also showing that these regions are sensitive to the effects of insulin, and these effects may be moderated by individual differences in anthropometric measures of relative adiposity or obesity." (PMID 24358272, 2013). "Besides, a study conducted in South Africa showed that 38% of women with proven obesity were found to be normally sensitive to insulin, and otherwise had an unremarquable cardiometabolic profile, corresponding to the Metabolically Healthy but Obesephenotype." (PMID 23503103, 2013). "In conclusion, the relationship between insulin sensitivity and circulating zonulin might be mediated through the obesity-related circulating IL-6 increase." (PMID 22629362, 2012). "Weight gain, glucose intolerance and reduced insulin responsiveness are hallmarks of obesity." (PMID 22514681, 2012). "Thus, palmitoleate supplementation also dissociates insulin resistance and liver inflammatory response from hepatic steatosis in mice with diet-induced obesity." (PMID 22768070, 2012). "The relationship between insulin sensitivity and circulating zonulin might be mediated through the obesity-related circulating IL-6 increase." (PMID 22629362, 2012). "Obesity may affect adrenocortical function by decreasing insulin sensitivity and inducing the secretion of adipocytokines." (PMID 23216997, 2012). "Insulin injected into the intracerebroventrical of the hypothalamus reduces food intake while inhibiting insulin receptors of the hypothalamic ARC nucleus causes hyperphasia and obesity in rodent models." (PMID 22876196, 2012). "In obesity, then, the leptin/insulin -> dopamine -> reward chain is inverted at each step." (PMID 22833718, 2012). "Fibroblast growth factor 21 (FGF21), whose expression is induced by peroxisome proliferator-activated receptor α (PPARα), has been recently identified as a novel metabolic regulator which plays a crucial role in glucose homeostasis, lipid metabolism, insulin sensitivity and obesity." (PMID 22394566, 2012). "However, under insulin-resistant conditions, the results of studies of food-induced or genetic obesity differed." (PMID 23272147, 2012).